PTHLH (parathyroid hormone like hormone)
Diseases named in the same sentence as PTHLH in open-access papers (continued):
Sharing a sentence is not in itself a finding about the gene and the disease.
postmenopausal osteoporosis (5 papers, 2015 to 2021). Metabolic disorder associated with fractures of the femoral neck, vertebrae, and distal forearm. "Moreover, one haplotype (rs12425376-rs10843047-rs42294) covering the 5’ end of PTHLH was associated with postmenopausal osteoporosis." (PMID 26568273, 2015).
bladder cancer (4 papers, 2022 to 2025). "Considering the high protein level of PTHLH in bladder cancer tissue, we next try to validate its association with M2 macrophages." (PMID 36439109, 2022). "Immunofluorescence indicated that the knockdown of PTHLH in bladder cancer cells can significantly inhibit the M2 polarization of co-culture M0 macrophages." (PMID 36439109, 2022). "Immunofluorescence showed that the knockdown of PTHLH in bladder cancer cells can significantly inhibit the M2 polarization of co-culture M0 macrophages, making it a potential biomarker for bladder cancer." (PMID 36439109, 2022). "Immunofluorescence showed that the knockdown of PTHLH in bladder cancer cells can significantly inhibit the M2 polarization of co-culture M0 macrophages." (PMID 36439109, 2022). "Immunofluorescence showed that knockdown of PTHLH in bladder cancer cells can significantly inhibit the M2 polarization of co-culture M0 macrophages." (PMID 36439109, 2022). "Meanwhile, data from the HPA database indicated a higher protein level of PTHLH in bladder cancer tissue." (PMID 36439109, 2022). "Meanwhile, data from the Human Protein Atlas database indicated a higher protein level of PTHLH in bladder cancer tissue." (PMID 36439109, 2022). "PTHLH-mediated M2 macrophage enrichment was identified in bladder cancer." (PMID 40894073, 2025). "Meanwhile, the PTHLH was identified as a novel biomarker for bladder cancer immunotherapy." (PMID 36439109, 2022). "However, the HPA database showed a high protein level of PTHLH in bladder cancer tissue." (PMID 36439109, 2022). "Our results indicated that PTHLH, BHMT2, and NGFR might be novel targets for bladder cancer immunotherapy and prognosis." (PMID 36439109, 2022). "We identified three genes, PTHLH, BHMT2, and NGFR, involved in bladder cancer immunotherapy." (PMID 36439109, 2022).
kidney cancer (4 papers, 2017 to 2026). Primary or metastatic malignant neoplasm involving the kidney. "Therefore, HIF likely regulates PTHLH in cancers beyond kidney cancer." (PMID 40964365, 2025). "Also, five parathyroid hormone-related proteins (PTHrPs) (PTHLH, PTH, HCRT, MC2R, and PTH2) are prominent for three kidney cancers (KICH, KIRC, and KIRP)." (PMID 28676692, 2017).
medulloblastoma (4 papers, 2011 to 2022). A malignant, invasive embryonal neoplasm arising from the cerebellum. "Finally, we correlated their expression with patient outcome finding that altered VCAM1, TP63, ANKRD1, THBS1, and PTHLH levels correlated with lower patient survival in Group 4 medulloblastoma samples." (PMID 32316671, 2020). "Next, we moved our attention to genes already related to medulloblastoma based on the literature and validated some of them, such as POSTN, BOC, VCAM1, and TP63 among the downregulated genes and ANKRD1, THBS1, NRG1, PTHLH, and HBEGF among the upregulated ones in DAOY and D283Med cells." (PMID 32316671, 2020).
endometritis (3 papers, 2016 to 2021). An acute or chronic, usually bacterial infectious process affecting the endometrium. "The expression patterns of only 28 genes in subclinical endometritis have been substantially altered, of which 26 genes including PTHLH, INHBA, DAPL1, MAOB, CXCR4, and TGIF1 were identified in both subclinical and clinical endometritis." (PMID 33426032, 2020). "There are 92 genes, including PTHLH, INHBA, DAPL1, and SERPINA1, which were significantly highly regulated and 111 genes which had significantly poorly regulated expression levels, including MAOB, CXCR4, HSD11B, and BOLA, as recorded in clinical endometritis." (PMID 33426032, 2020).
intrahepatic cholangiocarcinoma (3 papers, 2017 to 2022). A carcinoma that arises from the intrahepatic bile duct epithelium in any site of the intrahepatic biliary tree. "In summary, we report that ICC-secreted PTHLH acts in an autocrine manner in intrahepatic cholangiocarcinoma progression by activating the canonical ERK/JNK signaling pathway." (PMID 29178939, 2017).
pulmonary fibrosis (3 papers, 2012 to 2026). Chronic progressive interstitial lung disorder characterized by the replacement of the lung tissue by connective tissue, leading to progressive dyspnea, respiratory failure, or right heart failure. "parathyroid hormone-related protein (PTHrP) translated from PTHLH was significantly increased in the bronchial epithelium of IPF patients and bleomycin-induced pulmonary fibrosis mice." (PMID 41724741, 2026).
anaplastic thyroid carcinoma (2 papers, 2024 to 2025). "miR-200c post-transcriptionally targets the 3’ untranslated region (UTR) of parathyroid hormone-like hormone (PTHLH) mRNA, attenuating proliferation, invasion, and EMT progression in anaplastic thyroid carcinoma (ATC) models." (PMID 40530008, 2025).
brachydactyly (2 papers, 2021 to 2026). A disease characterized by the presence of brachydactyly, including syndromic and non-syndromic forms. "An identified microdeletion lying within the revised minimal critical region, containing only PTHLH and PPFIBP1 as disease genes, was described in a family with brachydactyly and learning disabilities, supporting the possible involvement of PPFIBP1 in the neurodevelopmental phenotype." (PMID 41595523, 2026).
cholangiocarcinoma (2 papers, 2017 to 2023). A carcinoma that arises from the intrahepatic biliary tree (intrahepatic cholangiocarcinoma) or from the junction, or adjacent to the junction, of the right and left hepatic ducts (hilar cholangiocarcinoma). "Growing evidences indicate that PTHLH-producing cholangiocarcinoma (CHO) patients suffer from humoral hypercalcemia of malignancy, but litter is known regarding PTHLH’s effect on ICC cells growth." (PMID 29178939, 2017).
developmental delay (2 papers, 2023 to 2025). "PTHLH plays an important role in chondrogenesis, brachydactyly, short stature, and developmental delay." (PMID 41373569, 2025).
fibroids (2 papers, 2016 to 2021). "Most of the leiomyoma DEGs were found upregulated in F compared to the MF or M; however, some genes, including CDKN1A, L1CAM, SLC7A5, CCND1, IGF1R, and PTHLH, were only increased in MF vs. M and F vs. M comparisons." (PMID 33807176, 2021).
glomerular diseases (2 papers, 2013 to 2025). "The interaction between PTHLH and PTH1R has been implicated in renal tubulointerstitial damage and glomerular diseases, including DKD." (PMID 40690456, 2025).
peripartum cardiomyopathy (2 papers, 2014 to 2022). Peripartum cardiomyopathy (PPCM) is an idiopathic, potentially fatal form of dilated cardiomyopathy that develops during the final month of pregnancy or within five months after delivery. "Moreover, a small genome-wide association study on 41 American peripartum cardiomyopathy samples showed an association with rs258415, in locus 12p11.22 close to the ParaThyroid Hormone-Like Hormone (PTHLH) gene." (PMID 25007941, 2014).
seminoma (2 papers, 2014 to 2023). A radiosensitive malignant germ cell tumor found in the testis (especially undescended), and extragonadal sites (anterior mediastinum and pineal gland). "Using TCGA mRNA expression of anabolic (CYP2R1, CYP27A1 and CYP27B1) and catabolic (CYP24A1) Vitamin D enzymes, positive (PTHLH, IFNG, and TNF) and negative (FGF23) feedback regulators could also clearly distinguish between pure seminomas and NSGCT." (PMID 37242266, 2023).
angiomyolipoma (1 paper, 2014). A neoplasm with perivascular epithelioid cell differentiation often associated with tuberous sclerosis. "High serum Ca concomitant with PTHLH overexpression in tumors was observed exclusively in clear cell RCC but not in other non clear cell subtype tumors, including papillary, chromophobe, collecting-duct, unclassified, and other rare subtype RCCs or in benign oncocytomas and angiomyolipomas." (PMID 24861371, 2014).
asthma (1 paper, 2024). "Among them, C3, PTGIR, CX3CL1, and PTHLH has important clinical diagnostic value and are correlated with infiltration of multiple immune cell types in asthma." (PMID 38640283, 2024). "C3, PTGIR, CX3CL1, and PTHLH have important clinical diagnostic values and are correlated with infiltration of multiple immune cell types in asthma." (PMID 38640283, 2024). "Among them, 4 genes validated by ROC curve analysis with AUC > 0.70 revealed potential diagnostic values for asthma, including C3, PTGIR, CX3CL1 and PTHLH." (PMID 38640283, 2024). "To further validate our findings, we analyzed the correlation between 4 hub genes (C3, PTGIR, CX3CL1, and PTHLH) and immune cell infiltration in asthma, This result indicates that C3, PTGIR, CX3CL1, and PTHLH expression were significantly correlated with the infiltration of immune cells." (PMID 38640283, 2024). "Therefore, we hypothesize that PTHLH may be a key target involved in the intestinal immune asthma link." (PMID 38640283, 2024).
collecting duct carcinoma (1 paper, 2014). "In contrast, all non clear cell tumor cases were plotted in the normocalcemia range with a relatively low-expression of PTHLH (≤0.213) except for one collecting-duct carcinoma case (#YUC667)." (PMID 24861371, 2014).
nasal polyps (1 paper, 2025). "Notably, CDH3 and PTHLH attained AUC values of 1, potentially influenced by the limited sample size of nasal polyps (NP) in the validation group (n = 27)." (PMID 40894073, 2025). "MRNA and protein levels of PTHLH and CDH3 were notably elevated in nasal polyp tissue compared to the control group, whereas PDCD4 and AR were downregulated (P < 0.05)." (PMID 40894073, 2025). "PTHLH, a secreted protein, is distributed across all layers of nasal polyps, and PDCD4 is primarily localized in the cytoplasm and nucleus of glandular epithelium within nasal polyps." (PMID 40894073, 2025).
neuroblastic tumor (1 paper, 2019). A group of nervous system tumors which display neuronal differentiation. "On the other hand, PTHLH is highly expressed in well‐differentiated, Schwannian stroma‐rich neuroblastic tumors and high levels of PTH1R expression are associated with MYCN nonamplified, benign neuroblastomas." (PMID 31293052, 2019). "Our initial data showed that PTHLH expression was detected in all groups of neuroblastic tumors, but the highest levels of expression were found in ganglioneuroblastomas and ganglioneuromas, two benign histologic subgroups that contain a high proportion of glial, Schwannian‐like cells." (PMID 31293052, 2019).
oncocytomas (1 paper, 2014). "A total of 656 primary renal tumors—that is, 542 clear cell, 43 papillary, 29 chromophobe, seven collecting-duct, 15 unclassified, or other rare subtype RCCs, 14 oncocytomas, and 6 AMLs—as well as 34 normal kidney tissue samples were analyzed for PTHLH mRNA expression." (PMID 24861371, 2014).
psoriasis (1 paper, 2009). An autoimmune condition characterized by red, well-delineated plaques with silvery scales that are usually on the extensor surfaces and scalp. "PTHLH agonists are effective therapies for psoriasis, an inflammatory skin disease characterised by epithelial hyper-proliferation." (PMID 19888454, 2009).
tumor (447 papers, 1991 to 2026). "PTHrP, which is the protein encoded by PTHLH, is mostly produced and expressed by many tumor tissues and just a few normal cells." (PMID 37555363, 2023). "In general, though, MMP1, MMP10 and PTHLH were mainly associated with poor prognosis, indicating a tumor promoting role in most cancers." (PMID 34301206, 2021). "PTHLH is regulated by gastrin and it is a growth factor regulator while p21 is a tumor suppressor that causes cell cycle arrest." (PMID 34439938, 2021). "As expected, the results revealed that ORM1 and PTHLH were associated with tumor immunity, such as antigen processing and presentation, T cell receptor signaling pathway and cytokine-cytokine receptor interactions." (PMID 33391264, 2020). "Parathyroid hormone like hormone (PTHLH) has previously been reported to be produced by tumour cells in the bone microenvironment and is implicated in osteoclastic activity and bone metastasis." (PMID 30517191, 2018). "Using data on tumor tissues from TCGA, we found that rs10843110, rs56318627 and rs11049453 within signal 3 were associated with the expression of PTHLH at P < 0.05 and CCDC91 at P < 0.10." (PMID 27459855, 2016). "PTHLH expression in primary human tumours was also reported to be associated with ERα positivity and reduced incidence of bone metastasis, as well as improved overall survival." (PMID 25633981, 2015). "We therefore examined the association between the VHL gene alteration status (intragenic mutation and promoter hypermethylation) and the tumor expression of PTHLH in selected clear cell RCCs (n = 244)." (PMID 24861371, 2014). "Rather, our data suggested that both the PTHLH upregulation and high serum Ca occurred as relatively late events during the tumor progression and were associated with aggressive phenotype." (PMID 24861371, 2014). "However, other reports have indicated that primary-tumour PTHLH-positivity is associated with poorer disease-free survival, an effect that is enhanced if co-expressed with the PTHLH receptor." (PMID 25633981, 2015). "PTHLH, also known as parathyroid hormone-related peptide (PTHrP), was initially identified as a tumor factor of humoral hypercalcemia of malignancy (HHM) and was later found to be expressed in a variety of tissue cells such as keratinocytes and follicles." (PMID 38419534, 2024). "We then defined the DEGs in PTHLH-high vs. PTHLH-low cells using pooled data from all tumor sub-types and performed functional pathways analyses using GSEA." (PMID 35440032, 2022). "We were able to define PTHLH-high and PTHLH-low subsets from the pooled sequencing data of 86,277 individual epithelial tumor cells." (PMID 35440032, 2022). "Meanwhile, the increased expression of the PTHLH can induce the cell cycle progression of tumor cells and actively regulate the expression of core proteins." (PMID 34796198, 2021). "Up to now, there are few reports on the association between EIF5A2, HGD, HS6ST1, PLS1, PTHLH, and YEATS2 methylation modification and tumor." (PMID 34796198, 2021). "PTHLH (parathyroid hormone related protein) is an important growth factor that exhibits pleiotropic effects, including tumor cell growth, death, and differentiation, which has been linked to the SHH pathway." (PMID 32316671, 2020). "In cancer, in vitro and in vivo evidences indicate that PTHLH promotes tumor initiation, growth and metastatic spread." (PMID 31293052, 2019).
tumor (continued). "To further explore the molecular basis of PTHLH-enhanced tumour development, we investigated the roles of PTHLH on metastasis using in vitro migration and Matrigel invasion assays." (PMID 29178939, 2017). "Using ChIP-qPCR assay, we demonstrated that RUNX2 binds directly to PTHLH promoter and thereby stimulates PTHLH expression which appears to be important for promoting tumor growth in Ca9-22 cells." (PMID 28120940, 2017). "In summary, our study not only reveals a novel positive feedback loop among RUNX2, PTHLH, and calcium but also shows RUNX2/PTHLH axis promotes HNSCC tumor growth." (PMID 28120940, 2017). "Despite the importance of PTHLH tumorigenic role, our knowledge of the PTH1R that mediate changes in the tumor progression and interaction with PTHLH in ICC is still limited." (PMID 29178939, 2017). "It was recently found that parathyroid hormone-like hormone (PTHLH) was frequently overexpressed in ICC compared with non-tumor tissue." (PMID 29178939, 2017). "PTHLH was predominantly restored the in vitro proliferation abilities (p < 0.05) and in vivo tumor growth abilities (p < 0.05)." (PMID 28120940, 2017). "IHC analyses of ICC tumor regions revealed strong staining of PTHLH compared with that in adjacent regions in the same patients." (PMID 29178939, 2017). "Our findings demonstrate that PTHLH knockdown in ICC cells suppressed tumor growth, while re-expression of PTHLH has the opposite effect, highlighting the role of PTHLH as a critical oncoprotein in ICC progression." (PMID 29178939, 2017). "Tumor-derived PTHLH participates in the bone metastatic processes of breast cancer via an intracrine fashion." (PMID 29178939, 2017). "We then enforced PTHLH expression in Ca9-22 cells to examine if PTHLH would promote HNSCC tumor growth." (PMID 28120940, 2017). "The high activity of PTHLH makes the blood vessels in the lung permeable enough to be passed by the tumour cells in order to colonise the lungs." (PMID 28105072, 2016). "Our research group have previously reported that PTHLH can act as a tumor promoter, affecting cell proliferation and the cell cycle in HNC27." (PMID 26857387, 2016). "Although this patient presented clinically with slightly high serum Ca, the qRT-PCR assay revealed that the tumor expression of PTHLH was at an undetectable level." (PMID 24861371, 2014). "Unlike parathyroid hormone (PTH), which is secreted only by the parathyroid gland, PTHrP, the protein encoded by PTHLH, is expressed and secreted by a few normal tissues and many tumor cells in an autocrine or paracrine way." (PMID 25539663, 2014). "We defined the cutoff value of the tumor PTHLH expression signal detected by qRT-PCR as 1.275 because of the finding that the majority of the clear cell RCC cases with high serum Ca belonged above this signal value in the correlation scattergram." (PMID 24861371, 2014). "In clear cell RCCs, the PTHLH expression levels in the tumor were positively correlated with symptomatic presentation, stage and grade as well as with poor patient OS." (PMID 24861371, 2014). "PTHLH has a broad range of functions, including roles in mammary gland development and tumor progression, making it a potential candidate gene." (PMID 22087758, 2011). "Moreover, TCGA analysis revealed that HNSC exhibits the highest overall PTHLH mRNA expression levels among the tumor types we examined." (PMID 40964365, 2025). "Additionally, the presence of RNA, which encodes oncogenes or tumor suppressor genes that are characteristically expressed in HNSCC, like SOX2, CRYAB, and PTHLH, further suggests transmission of tumor RNA into platelets." (PMID 37455825, 2023). "Estrogen can also affect PTHLH expression in the tissue which may enhance the tumor growth in the cartilaginous tissue." (PMID 37555363, 2023). "Interestingly, we found PTHLH derived from tumor cells can target macrophages and regulate the expression of CCL13, PLAU and ICAM1, resulting the phenotype of TAM_c1." (PMID 38044943, 2023).